PRM1 (protamine 1)
Diseases named in the same sentence as PRM1 in open-access papers (continued):
Sharing a sentence is not in itself a finding about the gene and the disease.
chronic leukemia (1 paper, 2023). A slowly progressing leukemia characterized by a clonal (malignant) proliferation of maturing and mature myeloid cells or mature lymphocytes. "Noteworthy, PRM1 was reported to be interacted with SEMG1 in chronic leukemia, which implied the functional relevance between PRM1 and SEMG1." (PMID 36593375, 2023).
chronic lymphatic leukemia (1 paper, 2023). "Since firstly identified as a CTA in chronic lymphatic leukemia, the aberrant expression of PRM1 in CRC was reported previously by a small sampled study." (PMID 36593375, 2023).
congenital megacolon (1 paper, 2023). "Next, we collected nonmalignant colonic epithelial tissues from two patients who underwent colectomy because of congenital megacolon and periappendiceal abscess, and performed western blot to compare PRM1 protein expression." (PMID 36593375, 2023).
COVID-19 (1 paper, 2022). A disease caused by infection with severe acute respiratory syndrome coronavirus 2. "At the same time, the expression of the classical marker genes TNP1, PRM1 and PRM2 of sperm were reduced in COVID-19." (PMID 36685935, 2022).
esophagus cancer (1 paper, 2023). "Aiming to explore novel biomarker with broad expression profile in digestive tract cancers, we revealed PRM1 upregulated in CRC, gastric cancer, and esophagus cancer." (PMID 36593375, 2023). "The result showed that PRM1 was upregulated in CRC tissues, gastric cancer tissues, and esophagus cancer tissues." (PMID 36593375, 2023).
melanoma (1 paper, 2022). A malignant, usually aggressive tumor composed of atypical, neoplastic melanocytes. "We also successfully activated PRM1 in the melanoma M375A cancer cell line (data not shown)." (PMID 35783678, 2022).
nephritis (1 paper, 2015). Inflammation of renal tissue. "The antibodies against PRM1 and PRM2 were detected in the sera from SLE patients with and without nephritis, although these positive signals were weak." (PMID 26098692, 2015).
prostate adenocarcinoma (1 paper, 2016). "Hence, a RT-PCR based approach was also used to clarify which promoters within the TBXA2R, namely Prm1 or Prm3, are regulating TPα and TPβ expression in human prostate tissue or in the prostate adenocarcinoma LNCaP and PC-3 cell lines." (PMID 27689401, 2016).
prostate neoplasm (1 paper, 2016). A neoplasm (disease) that involves the prostate gland. "Significant changes in the methylation landscape within the Prm1 and Prm3 regions of the TBXA2R were observed across a range of benign, precursor prostate neoplasms and increasing PCa staging." (PMID 27689401, 2016).
tumor (5 papers, 2016 to 2025). "Besides, the biofunctions and underlying cellular mechanism were well illustrated that PRM1 is involved in tumor metabolism rewiring under nutrition deficient conditions." (PMID 36593375, 2023). "Analyzed by qPCR, PRM1 mRNA expression was significantly elevated in 61.1% (55/90) of tumor tissues as compared with adjacent normal tissues." (PMID 36593375, 2023). "Similar to commonly used tumor markers, levels of serum PRM1 was also influenced by some pathological conditions, including inflammatory and benign proliferation lesions." (PMID 36593375, 2023). "Functional research carried out in this work revealed that PRM1 is involved in tumor growth regulation, especially under nutrient limitation." (PMID 36593375, 2023). "Efforts will also be taken to develop PRM1-based tumor immunotherapy strategies, either in forms of cancer vaccine or antibody-based treatment." (PMID 36593375, 2023). "The decrease in the proliferation of HEK293T cells, which are considered tumorigenic, indicates that PRM1 can reduce tumor cell proliferation and presents a promising approach in cancer therapy." (PMID 35783678, 2022). "Inspired by distinct cellular location in CRC cytosol and some glandular lumen, we hypothesized that PRM1 protein might be secreted by tumor cells to extracellular space and into patients’ circulation." (PMID 36593375, 2023). "Cancer vaccine composed of PRM1 epitope may facilitate tumor control by induction of specific immune response, since we have demonstrated that anti-PRM1 can be used as an antagonist of secreted PRM1 to inhibit CRC tumorigenesis and cell proliferation." (PMID 36593375, 2023). "Secreted by CRC cells, PRM1 might be considered as a growth factor to activate PI3K/AKT/mTOR pathway stimulating tumor growth." (PMID 36593375, 2023). "Recently, PRMT1 has indicated that PRM1 may have oncogenic function in tumor cells." (PMID 40612681, 2025). "Thus, investigating the role of PRM1 in different tumor types is warranted." (PMID 35783678, 2022). "To verify the upregulated expression of PRM1 in CRC, we collected a total of 90 paired CRC and adjacent normal tissues (defined as five cm from the tumor edge)." (PMID 36593375, 2023).
cancer (3 papers, 2022 to 2024). A tumor composed of atypical neoplastic, often pleomorphic cells that invade other tissues. "In sum, we demonstrated that circANXA4 promotes cancer cell proliferation and progression by sponging miR-1256 and upregulating PRM1 in CRC." (PMID 38660591, 2024). "Furthermore, we examined PRM1 expression in cancer and adjacent tissues by qRT-PCR." (PMID 38660591, 2024).
infection (1 paper, 2021). The state of being infected such as from the introduction of a foreign agent such as serum, vaccine, antigenic substance or organism. "In summary, we identified three ZIKV amino acids (C-106, prM-1, and NS5-872) that we show for the first time affect transmission by increasing infection and transmission efficiency by A. aegypti and/or enhancing replication in models for human infection." (PMID 33500409, 2021).
PRM1 also shares sentences with these, for which no sentence is quoted: colorectal cancer (3 papers); oligospermia (2); acute appendicitis (1); adenocarcinoma (1); breast carcinoma (1); colorectal adenoma (1); Crohn`s disease (1); gastric cancer (1); infectious disease (1); inflammatory bowel disease (1); leukemia (1); lymph node metastasis (1); proliferative inflammatory atrophy (1); prostatic intraepithelial neoplasia (1); Sertoli Cell-Only Syndrome (1); toxoplasmosis (1); ulcerative colitis (1).